IL6 (interleukin 6)
Diseases named in the same sentence as IL6 in open-access papers (continued):
Sharing a sentence is not in itself a finding about the gene and the disease.
cardiac arrest (continued). "We compared serum levels of the proinflammatory cytokine interleukin-6 (IL6) measured with two rewarming rates after TTM at 33 °C in patients with shockable out-of-hospital cardiac arrest (OHCA)." (PMID 34920723, 2021). "Cardiac arrest led to increased IL-6 levels at 1 h post-ROSC (baseline vs. 1 h post-ROSC, 92.1 ± 13.7 pg/mL vs. 120.5 ± 42.5 pg/mL, p < 0.0001)." (PMID 35011872, 2021). "Increased IL-6 expression has been recently reported to correlate with a poor neurological outcome in post-cardiac arrest patients." (PMID 31821351, 2019). "In contrast to IL6, we found that syndecan-1 is still being released at 24 h, hypothetically due to other factors than the initial cardiac arrest-induced ischemic insult, like further persistent shock states or aggressive vasopressor and fluid treatment." (PMID 31148947, 2019). "A pro-inflammatory response has been seen in patients with T2DM outside the setting of cardiac arrest, as several studies have shown, e.g., increased levels of IL-6 in T2DM patients." (PMID 30088108, 2018). "Cytokine cutoffs for predicting poor neurological outcome following cardiac arrest were 1423 pg/mL for IL-8 and 2708 pg/mL for IL-6 (both with sensitivity of 100% and specificity of 86%)." (PMID 28487810, 2017). "IL-8 and IL-6 were found to be significantly higher in subjects who had experienced cardiac arrest, and both cytokines were found to be correlated with poor neurological outcome." (PMID 28487810, 2017). "In muscle, similar differences between “cardiac arrest group” animals and “injury group” were also seen, along with marked increases in IL-18, IL-1α, IL-6, IFNγ, and MCP-1." (PMID 26635801, 2015). "This differential response of IL-6 to rewarming in patients with a poor or favorable outcome could not be determined in our cohort of patients, which is probably due to the small number of patients or the different underlying pathophysiology (brain death versus cardiac arrest)." (PMID 25304549, 2014). "Similarly, in a clinical trial known as “IL-6 Inhibition for Modulating Inflammation After Cardiac Arrest” (IMICA), 80 comatose patients with out-of-hospital cardiac arrests were randomly assigned to a single infusion of tocilizumab versus placebo." (PMID 39583411, 2024). "Consequently, this study demonstrated the time-course of changes in IL-6 levels across the overall spectrum of cardiac arrest phenotypes." (PMID 39199472, 2024). "In the settings of severe infection, high levels of IL-6 combined with AZM and HCQ, can cause fatal arrhythmias and cardiac arrest via excessive conduction abnormalities, prolongation of the QTc and APD as a result of the multi-channels’ inhibition of INa, ICaL and IKr." (PMID 35058480, 2022). "Similarly, in two prospective observational studies of patients with out-of-hospital cardiac arrest (OHCA), IL6 elevation at ICU admission was independently associated with poorer functional outcomes." (PMID 34920723, 2021). "Epoxide hydrolases are also involved in the regulation of neuroinflammation and inhibition of soluble epoxide hydrolases resulted in decreased pro-inflammatory cytokines (IL-1β and Il-6) within the context of seizures, and increased IL-10 secretion in the CNS following cardiac arrest." (PMID 29040522, 2018). "The pattern of alteration was similar in the Fingolimod group, except for IL-6 blood levels that were significantly decreased vs Control at 2 and 6 h following cardiac arrest (e.g., 5.6 ± 4.8 vs 59.4 ± 20.6 pg/ml at 2 h following cardiac arrest in Fingolimod vs Control, respectively)." (PMID 38954057, 2024). "In cardiac-arrest survivors, NHR showed a higher ROC-AUC of 0.74, outperforming CRP (0.58) and slightly exceeding IL-6 (0.69), indicating better prediction of adverse outcomes." (PMID 41162914, 2025).
cardiac arrest (continued). "On the other hand, adiponectin secreted by visceral fat inhibits the release of pro-inflammatory molecules such as interleukin-6 (IL-6) and tumor necrosis factor-α (TNF-α) after cardiac arrest, alleviating systemic inflammatory responses." (PMID 41450519, 2025). "Although IL-6 is present in the cerebrospinal fluid and brain, it remains undetermined whether the elevation in IL-6 levels after initiation of a systemic response by cardiac arrest is due to release from the cerebrospinal fluid or from necrotizing brain cells." (PMID 35711345, 2022). "According to previous studies, the following biomarkers predict outcome after cardiac arrest and ROSC: interleukin-6, high-sensitivity C-reactive protein, serum neuron-specific enolase concentration, and S-100 protein." (PMID 33833877, 2021). "Cardiac arrest and ECPR markedly increased the plasma levels of IL-10, VEGF, leptin, TNF-α, IL-1β, IL-6, fractalkine, IL-5, IL-18, IP-10, IL-4, eotaxin, MIP-1α, IL-17α, IL-12, RANTES, G-CSF, LIX, and MCP-1." (PMID 34781966, 2021). "Serum HMGB1 for first 24 h after cardiac arrest was significantly correlated with SOFA score, NSE, and IL-6." (PMID 28950909, 2017). "Our study indicates that serum HMGB1 for first 24 h after cardiac arrest significantly correlates with SOFA score, NSE, and IL-6." (PMID 28950909, 2017). "In conclusion, compared to rewarming at 0.5 °C/H, rewarming at 0.25 °C/h after hypothermia at 33 °C for 24 h did not decrease serum IL6 levels in patients who remained comatose after cardiac arrest in a shockable rhythm." (PMID 34920723, 2021). "140-character Tweet: Rewarming at 0.25 °C versus 0.50 °C did not decrease serum IL6 levels after hypothermia at 33 °C in patients comatose after shockable cardiac arrest." (PMID 34920723, 2021). "Take-Home Message: Rewarming at a rate of 0.25 °C/h, compared to 0.50 °C, did not result in lower serum IL6 levels after achievement of hypothermia at 33 °C in patients who remained comatose after shockable cardiac arrest." (PMID 34920723, 2021). "Therefore, we suggest that the narrow selection bias raises questions regarding the generalizability of the neuroprotective effect of tocilizumab against IL-6 because their limited cohort did not represent the full spectrum of cardiac arrest severity." (PMID 39199472, 2024). "Given this limitation and the lack of an association between IL-6 and NSE in patients with low-severity cardiac arrest, the brain inflammatory response that can exacerbate HIBI after cardiac arrest is insufficient for determining the neuroprotective effect of tocilizumab." (PMID 39199472, 2024). "Our data provide evidence that in the setting of inflammation characterized by high IL-6 titers, the use of medications such as AZM + HCQ increases the arrhythmogenic risk with the potential for cardiac arrest without any significant changes in IL6R gene expression by AZM + HCQ." (PMID 35058480, 2022). "Our observations of the protective effects of IL-6 and the negative correlation with in-hospital mortality suggest that future comprehensive studies should be performed to evaluate the roles of individual cytokines in cardiac arrest." (PMID 27256246, 2016). "These clinical findings are consistent with our observation that the combination of IL-6 + AZM + HCQ, but not AZM + HCQ, results in marked bradycardia, QTc prolongation and cardiac arrest (asystole)." (PMID 35058480, 2022). "In the brain 2 h post-ROSC, cardiac arrest and CPR led to an increase in the mRNA levels of IL-6, IL-1β, and TNF-α, but not HMGB-1." (PMID 35011872, 2021).
gestational diabetes (48 papers, 2015 to 2026). Carbohydrate intolerance first diagnosed during pregnancy. "An increase in the level of several cytokines and in particular IL-6 has been reported in coronavirus disease-19 (COVID-19) infection and increased the risk of adverse prenatal outcomes such as gestational diabetes." (PMID 34007846, 2021). "Furthermore, serum Il-6 levels have been suggested to be considered as a diagnostic biomarker for gestational diabetes mellitus." (PMID 38893732, 2024). "Increased levels of TNF-α and IL-6 may contribute to placental dysfunction, impaired nutrient transport, and inflammatory disruption of the utero-fetal interface, factors that have been implicated in the pathogenesis of gestational diabetes mellitus." (PMID 40722699, 2025). "Postpartum women with gestational diabetes have a unique inflammatory profile characterized by reduced IL-6 and MCP-1 levels." (PMID 40062150, 2025). "Sph and BID positively correlated with Th17/Treg ratio, and Sph positively correlated with Th17, IL-6 levels and gestational diabetes." (PMID 41573549, 2025). "Reduced levels of TNF-α, IL-1β, and IL-6 during KLF9 silencing suggest suppressed inflammation in gestational diabetes mellitus." (PMID 37940560, 2023). "A further study has reported that in vitro treatment using AR-42 enhances the secretion of IL-1β, TNFα and IL-6 in monocytes obtained from patients with gestational diabetes mellitus." (PMID 37728477, 2023). "High levels of IL-6 and TNF-α have been positively associated with gestational diabetes mellitus (GDM)." (PMID 33806342, 2021). "Women with gestational diabetes have higher concentration of inflammatory cytokines including IL-6, IL-10, and TNF-α compared with healthy pregnant women." (PMID 29385062, 2018). "TNF-α, IL-1β, and IL-6 are essential in early pregnancy, but, with the evolution of gestation, high TNF-α levels can promote preeclampsia and gestational diabetes mellitus, while low IL-10 levels are associated with preterm birth." (PMID 27294162, 2016). "Statistical analysis of the data showed that there was a statistically significant difference in IL-6 concentrations at the p < 0.05 level between the group of pregnant women with gestational diabetes and complications (Group 4) compared to the remaining three groups of subjects." (PMID 40941639, 2025). "Gestational diabetes-related immune dysregulation has been shown to lead to increased maternal IL-6 with enhanced placental leptin production but a paradoxical reduction in the IL-6 levels of the LGA offspring, possibly related to the hyperleptinemia that is typically seen in LGA infants." (PMID 35197933, 2022). "Furthermore, systemic inflammation during pregnancy, defined as elevated serum levels of C-reactive protein (CRP) and/or interlukin-6 (IL-6), may serve as a precursor to gestational diabetes mellitus (GDM)." (PMID 33552314, 2021). "A previous study suggested that pEVs from patients with gestational diabetes mellitus (GDM) activate endothelial cells, leading to high level of cytokine secretion, including IL-4, IL-6, IL-8, IFN-γ, TNF-α." (PMID 39996028, 2025). "Serum IL-6 and MCP-1 levels were significantly reduced in the gestational diabetes group compared with the control group, while IL-18 levels were not significantly different." (PMID 40062150, 2025). "Accordingly, IL-6, IL-18, and MCP-1 were selected as inflammatory biomarkers, given their potential alterations during gestational diabetes." (PMID 40062150, 2025). "Expression levels of chemerin, IL-6, and TNF-α are increased in the peripheral blood of patients with gestational diabetes." (PMID 37964253, 2023). "Crocetin decreased the expression levels of IL-6, TNF-α, and IL-1β, increased the levels of antioxidant enzymes such as SOD, GSH-Px, GSH, and CAT, and increased body weight in rats with STZ-induced gestational diabetes mellitus (GDM)." (PMID 38004168, 2023).
gestational diabetes (continued). "The expression of chemerin, fatty acid binding protein 4 (FABP4), and the inflammatory factors IL-6 and TNF-α are increased in the peripheral blood of gestational diabetes patients." (PMID 37964253, 2023). "The aim of this review is to highlight the influence of the Mediterranean Diet (MedDiet) on Gestational Diabetes Mellitus (GDM) and Gestational Weight Gain (GWG) during the COVID-19 pandemic era and the specific role of interleukin (IL)-6 in diabesity." (PMID 33530554, 2021). "In a meta-analysis of five RCTs that included women with gestational diabetes, probiotic supplementation led to a significant reduction in CRP (p < 0.0001), IL-6 (p = 0.0005), and malondialdehyde (MDA) (p < 0.00001), and an increase in NO (p = 0.003) and total antioxidant capacity (TAC) (p = 0.01)." (PMID 37764004, 2023). "Thus, gestational diabetes is accompanied by increased expression of TNF-α and IL-6, with the exacerbation of an inflammatory state in the placenta." (PMID 37964253, 2023). "Our study showed that IL-6, TNF-α, and IR had a certain correlation, suggesting that TNF-α and IL-6 could be used as important indicators for the detection and diagnosis of gestational diabetes mellitus." (PMID 32280713, 2020). "This study suggests that IL-6 and TNF-α are correlated with gestational diabetes mellitus." (PMID 32280713, 2020). "Interestingly it has previously been reported that women with gestational diabetes mellitus show elevated serum levels of CRP, IL-6 and TNF-α." (PMID 25806806, 2015). "In addition, AsIV also reduced inflammatory genes IL-6 and TNF-α and suppressed NACHT, LRR, and PYD domain-containing protein 3 (NLRP3) inflammasome-related proteins in the pancreas of gestational diabetes mellitus (GDM) mice, leading to lower blood glucose and insulin levels." (PMID 41011612, 2025). "Furthermore, women with gestational diabetes were found to have lower levels of IL-6 and MCP-1, but not IL-18." (PMID 40062150, 2025). "An analysis of the blood of patients with gestational diabetes mellitus (GDM) has demonstrated reduced CD4+CD25+ Treg cell numbers and increased pro-inflammatory cytokines IL-6 and TNF-a." (PMID 38732104, 2024). "Furthermore, the current study suggests that IL-6 and TNF-α are correlated with gestational diabetes mellitus, but further study is necessary to explain whether they have causal relationship." (PMID 32280713, 2020). "Whether polymorphisms in tumor necrosis factor-α (TNF-α), interleukin-6 (IL-6), interleukin-10 (IL-10) or adiponectin (ADIPOQ) influence the risk of gestational diabetes mellitus (GDM) or not remain inconclusive." (PMID 32963590, 2020). "Given the compelling evidence that inflammatory markers play a role in pre-term births, including IL-6 and TNF-alpha, this work adds to the literature by suggesting that these markers may operate through onset of medical conditions in pregnancy, such as gestational diabetes." (PMID 31568495, 2019). "Adipocytes secrete pro-inflammatory cytokines such as TNF-α, IL-6, and CRP, which interfere with immunological tolerance during pregnancy, promote oxidative stress, and impair endothelial nitric oxide (NO) production—hallmarks of preeclampsia and gestational diabetes mellitus (GDM)." (PMID 40981180, 2025).
renal dysfunction (48 papers, 2009 to 2026). "Elevated concentrations of IL-6 have been linked to adverse postnatal outcomes including pulmonary injury, renal dysfunction, gut inflammation, and neural injury." (PMID 40710297, 2025). "Experimental studies indicate that renal dysfunction is associated with elevated pro-inflammatory cytokines (e.g., IL-6), which in preclinical models can enhance tumor angiogenesis and metastatic potential." (PMID 40657251, 2025). "Urine levels of IL-6 modestly correlate with its plasma levels, and increased urinary IL-6 is associated with cardio-renal dysfunction indicating tissue-specific inflammation." (PMID 35625822, 2022). "Importantly, a significant correlation was found between VCAM-1 and the Horowitz index (r = 0.3115), PCT (r = 0.3664), IL-6 (r = 0.4599) and E-selectin (r = 0.3643), while an inverse association was analyzed with renal dysfunction evaluated by GFR (r = −0.5076)." (PMID 38276214, 2024). "A research containing 98 HF patients found that increased plasma IL-6 concentration was correlated with higher mortality risk, whereas elevated urine IL-6 level (quantify inflammation at the level of renal tissue) was independently associated with renal dysfunction." (PMID 34276413, 2021). "Several reports show that high IL-6 levels are correlated with renal dysfunction in patients with PD." (PMID 40143028, 2025). "PQ exposure raises pro-inflammatory cytokines like Tumor necrosis factor alpha (TNF-α) and Interleukin 6 (IL-6), which further mediate inflammation and renal dysfunction." (PMID 41509108, 2025). "Renal dysfunction has been proven to increase the cytokines level in our body, including interleukin -1, IL-6, and tumor necrosis factor-α." (PMID 37041544, 2023). "While we expected that peripheral markers would correlate positively with urine markers, most of the studies showing a positive correlation between serum and urine IL-6 levels have been conducted in patients with renal dysfunction." (PMID 36299996, 2022). "Increased circulating IL-6 was reported in congestive HF patients, which had a significantly positive correlation with worsening cardiac symptom and renal dysfunction." (PMID 34276413, 2021). "Low magnesium was significantly and strongly associated with increased BMI, heavy drinking, AF, renal dysfunction, use of antihypertensive drugs, HOMA-IR, CRP, IL-6, vWF, cTnT and NT-proBNP." (PMID 29663176, 2018). "Similarly, renal dysfunction increases plasma levels of pro-inflammatory cytokines, including interleukin-6, tumor necrosis factor-α, and monocyte chemotactic protein-1, promoting vascular inflammation." (PMID 40129657, 2025). "Interestingly, we also report that a high serum level of IL-1β and IL-6 correlates with a low EF (cardiac dysfunction) and with high levels of both creatinine (renal dysfunction) and ALT (liver injury)." (PMID 39559354, 2024). "Thus, a high serum level of both IL-1β and IL-6 correlated with a low EF (cardiac dysfunction) and with high levels of both creatinine (renal dysfunction) and ALT (liver injury)." (PMID 39559354, 2024). "In addition to high levels of C-reactive proteins (CRP), D-dimer, procalcitonin (PCT), total bilirubin, renal dysfunction indices, and interleukin-6 levels (IL-6), as well as low lymphocyte counts, were found to predict a severe disease course and death." (PMID 37048734, 2023). "Notably, in cirrhotic ascitic rats from our study, chronic pioglitazone pre-treatment attenuated LPS-induced TNFα/NFκB-mediated acute on chronic renal dysfunction by suppressing renal IL-6, ICAM-1 and VCAM-1." (PMID 34831270, 2021). "hsCRP; IL-6; C4; clinical outcomes (renal dysfunction, ventilation)." (PMID 19840397, 2009). "However, our multivariable regression analysis indicates that coagulopathy, but not elevated IL-6, is associated with increasing odds of acute liver injury, renal dysfunction and ARDS." (PMID 33564286, 2021).
renal dysfunction (continued). "We observed that increased urinary secretion of MCP-1 and IL-6 in HHTg rats was accompanied by decreased urinary secretion of EGF, another promising marker of early renal dysfunction." (PMID 31886287, 2019). "When stratified by eGFR and CFR, in women with renal dysfunction, CRP, IL-6, and SAA were higher in those with low CFR compared with those with normal CFR." (PMID 25951606, 2015). "Patients with hypomagnesemia, vasopressor requirements, or biomarkers indicative of neuroinflammation (e.g., elevated IL-6, MMP9) may derive greater benefit, whereas those with hypermagnesemia or advanced renal dysfunction require cautious dosing." (PMID 40552120, 2025). "In this work, the highest levels of IL-6, CCL2 gene expression and IL-10 release and the lowest transcript levels of CCR2, which reflects monocyte maturation, have been observed after treatment with IS at concentrations found in subjects with moderate renal dysfunction." (PMID 26925780, 2016).